ENSG00000262202 (novel transcript)
Gene: Long non-coding RNA gene on chromosome 17 (19,111,680 to 19,190,245, reverse strand). Ensembl gene ENSG00000262202.
Gene Ontology:
Biological process: RNA processing
Cellular component: nucleolus